PPIH (peptidylprolyl isomerase H)
Diseases named in the same sentence as PPIH in open-access papers:
PPIH is named in the same sentence as 25 diseases in open-access papers, as found by Europe PMC text mining. Sharing a sentence is not in itself a finding about the gene and the disease. The quoted sentences say what the papers report.
breast carcinoma (3 papers, 2019 to 2025). "The analysis revealed that the co-expressed genes, mostly associated with PPIH in breast cancer, were significantly involved in the cell cycle and spliceosome pathways." (PMID 38834966, 2024). "Boxplot analyses revealed that breast cancer specimens exhibited significantly higher PPIH mRNA expression than normal tissues." (PMID 38834966, 2024). "This study is the first to report that PPIH mRNA and protein levels are markedly elevated in LIHC, Colon adenocarcinoma (COAD), and Breast cancer (BC), and are associated with a worse prognosis in these cancer patients." (PMID 38834966, 2024). "For module #35, while most of the genes locate on 1q34, many of the genes such as UQCRH, PSMB2, PPIH, and YBX1 are involved in RNA processing and have been identified with breast cancer in multiple studies." (PMID 30906311, 2019).
hepatocellular carcinoma (3 papers, 2023 to 2025). A malignant tumor that arises from hepatocytes. "Collectively, these findings elucidate the important functions of PPIH in promoting hepatocellular carcinoma progression and modulating the tumor microenvironment." (PMID 40895540, 2025). "To validate the results from public database analyses, we assessed PPIH expression in hepatocellular carcinoma (HCC)." (PMID 40895540, 2025). "Integration with hepatocellular carcinoma single-cell RNA sequencing data further elucidated the potential regulatory role of PPIH within the TME." (PMID 40895540, 2025). "Our previous studies have indicated that mRNA and protein levels of PPIH are significantly upregulated in Hepatocellular Carcinoma (LIHC) and could act as predictive biomarkers for patients with LIHC." (PMID 38834966, 2024). "Consistently, in vitro assays demonstrated that increased expression of PPIH promotes the proliferation, migration, and invasion of hepatocellular carcinoma (HCC) cells." (PMID 40895540, 2025). "The results revealed that PPIH was significantly upregulated in various cancer types, including cholangiocarcinoma (CHOL), colorectal adenocarcinoma (COAD), esophageal carcinoma (ESCA), hepatocellular carcinoma (LIHC), and stomach adenocarcinoma (STAD)." (PMID 40895540, 2025).
gastric adenocarcinoma (2 papers, 2024 to 2025). "Interestingly, PPIH overexpression was paradoxically associated with favorable prognosis in stomach adenocarcinoma (STAD) and ovarian serous cystadenocarcinoma (OV), suggesting a potential context-dependent or stage-specific dual role of PPIH in tumor progression." (PMID 40895540, 2025).
gastric cancer (2 papers, 2024 to 2025). A primary or metastatic malignant neoplasm involving the stomach. "Conversely, serum PPIH levels are decreased in patients with these tumors (LIHC, COAD, BC, gastric cancer), and when combined with traditional tumor markers, offer enhanced sensitivity and specificity for diagnosis." (PMID 38834966, 2024). "Further characterization revealed that the cis-eQTL effects of PPIH showed a positive correlation with the GWAS effects in esophageal cancer but negative correlations in gastric cancer and clear cell renal cell carcinoma." (PMID 40895540, 2025). "Furthermore, PPIH expression correlates significantly with immune cell infiltration in HCC, gastric cancer (GC), and CHOL, suggesting that its pro-tumorigenic effects may be mediated via modulation of the TME." (PMID 40895540, 2025).
adrenocortical carcinoma (1 paper, 2025). "Similarly, negative correlations were observed between PPIH expression and all four survival indicators in liver hepatocellular carcinoma (LIHC), adrenocortical carcinoma (ACC), and prostate adenocarcinoma (PRAD)." (PMID 40895540, 2025).
bone sarcoma (1 paper, 2023). A sarcoma that arises from the bone. "In bone sarcoma cell lines, drug/protein associations included a strong association of protein abundance of peptidyl-prolyl cis-trans isomerase H (PPIH) with response to the Aurora kinase B/C selective inhibitor GSK1070916." (PMID 37197427, 2023).
breast invasive carcinoma (1 paper, 2025). "In terms of OS and DSS, high PPIH expression predicted significantly worse outcomes in multiple cancers, including LIHC, ACC, and breast invasive carcinoma (BRCA), while indicating improved survival in OV and select other cancer types." (PMID 40895540, 2025).
colon adenocarcinoma (1 paper, 2024). "We observed overexpression of PPIH in colon adenocarcinoma tissues relative to normal tissues." (PMID 38834966, 2024).
glioblastoma (1 paper, 2020). The most malignant astrocytic tumor (WHO grade IV). "We also observed changes in expression of four RNA processing regulators previously identified in genomic/functional screening for RNA binding proteins contributing to glioblastoma phenotypes: MAGOH, PPIH, ALYREF, and SNRPE70." (PMID 32488114, 2020).
liver cancer (1 paper, 2024). An epithelial or non-epithelial malignant neoplasm that arises from the liver. "We also validated abnormal PPIH expression in human liver cancer tissues, and immunohistochemical analyses revealed a correlation between PPIH protein expression and mRNA levels in LIHC, COAD and BC specimens." (PMID 38834966, 2024). "Similarly, PPIH mRNA expression was elevated in liver cancer tissues compared to adjacent normal liver tissues." (PMID 38834966, 2024).
pancreatic adenocarcinoma (1 paper, 2025). "Notably, high PPIH expression was significantly correlated with shorter OS, DSS, and PFI in pancreatic adenocarcinoma." (PMID 40895540, 2025).
testicular germ cell tumor (1 paper, 2025). A germ cell tumor arising from the testis. "Clinicopathological correlation analysis using the GEPIA2 platform revealed that PPIH expression was significantly associated with tumor stage in several cancer types, including CHOL, kidney chromophobe (KICH), kidney renal clear cell carcinoma (KIRC), LIHC, and testicular germ cell tumors (TGCT)." (PMID 40895540, 2025).
cancer (4 papers, 2019 to 2025). A tumor composed of atypical neoplastic, often pleomorphic cells that invade other tissues. "Our study corroborates these findings by demonstrating that PPIH is overexpressed in multiple cancer types and is associated with poor clinical outcomes, thereby strengthening its credibility as a pan-cancer biomarker." (PMID 40895540, 2025). "Further multi-omics analyses confirmed the potential utility of PPIH as a pan-cancer diagnostic and prognostic biomarker gene." (PMID 40895540, 2025). "Elevated PPIH expression was predominantly associated with poor prognosis, acting as a potential risk factor in numerous cancer types." (PMID 40895540, 2025). "We also assessed the association between PPIH expression and overall survival (OS) in cancer patients using Kaplan-Meier analysis with TCGA database information." (PMID 38834966, 2024). "Conversely, in certain cancers, high PPIH expression is linked to improved prognosis, indicating a possible dual role that may depend on tumor subtype-specific contexts." (PMID 40895540, 2025). "The repeated significant association of PPIH across multiple cancer types suggests that it may serve as a key gene with pan-cancer relevance." (PMID 40895540, 2025). "Among the candidates, PPIH emerged as a potentially causal gene common to all three cancers." (PMID 40895540, 2025). "Notably, PPIH exhibited consistently significant associations across all three cancer types, suggesting that its expression levels may be closely linked to the risk of multiple cancers, thereby implying a potential role in tumorigenesis." (PMID 40895540, 2025). "Overall, multi-omics analyses demonstrate that PPIH plays a pivotal role in cancer immune regulation and tumor progression." (PMID 40895540, 2025). "We performed a comprehensive multi-omics analysis to elucidate the potential role of PPIH in cancer immunity and tumorigenesis." (PMID 40895540, 2025). "Collectively, these findings underscore the clinical relevance of PPIH as both a biomarker and a putative oncogenic contributor in cancer." (PMID 40895540, 2025). "In summary, our findings reveal a potential oncogenic role of PPIH in multiple malignancies and lay a foundation for further investigation of PPIH as a pan-cancer key gene." (PMID 40895540, 2025). "The survival analysis in this study highlights the clinical significance of PPIH as a prognostic biomarker across various cancer types." (PMID 40895540, 2025). "The elevated expression of PPIH across multiple cancer types suggests its potential involvement in key oncogenic processes." (PMID 40895540, 2025). "Immune infiltration analysis based on XCELL, CIBERSORT-ABS, and EPIC algorithms revealed that PPIH expression was significantly correlated with the infiltration levels of various immune cell subsets across cancer types." (PMID 40895540, 2025). "On the genomic level, PPIH alterations were profiled across 33 cancer types using the cBioPortal platform." (PMID 40895540, 2025). "Given the complex nature of cancer prognosis, we further explored the effect of PPIH dysregulation on DFI and PFI." (PMID 40895540, 2025). "This study highlights PPIH as a candidate biomarker with pan-cancer relevance and potential clinical value." (PMID 40895540, 2025). "Among the three malignant tumor GWAS datasets included, PPIH was identified as a common critical gene across different cancer types and was therefore selected as a candidate target for further in-depth investigation." (PMID 40895540, 2025). "Through pan-cancer analysis, we found that the expression levels of PPIH mRNA in multiple tumors were significantly different from those in normal tissues." (PMID 38834966, 2024). "Through bioinformatics analysis utilizing open-access databases, we explored differences in PPIH mRNA expression in pan-cancer, and subsequently we meticulously examined PPIH expression in LIHC, COAD, and BC, assessing its correlation with patient outcomes." (PMID 38834966, 2024).
cancer (continued). "We evaluated PPIH’s potential as a serological marker to distinguish cancer patients from healthy individuals." (PMID 38834966, 2024). "We first examined mRNA sequencing data from the TCGA database, where we detected significant differences in PPIH expression between tumors and normal tissues for 16 cancers, after which we focused on evaluating samples from LIHC, COAD, and BC." (PMID 38834966, 2024). "By analyzing the TCGA dataset, we found that the expression of PPIH in cancer tissues was significantly different from that in normal tissues." (PMID 38834966, 2024). "This divergent pattern suggests that PPIH may exert distinct mechanisms of action across different cancer types." (PMID 40895540, 2025). "Notably, prior studies have primarily focused on the context-dependent functions of PPIH within individual cancer subtypes, often relying on single-cohort analyses with limited sample sizes and lacking systematic evaluation." (PMID 40895540, 2025). "First, despite leveraging GWAS datasets of multi-cancers, we did not identify genetic variants significantly associated with PPIH protein expression." (PMID 40895540, 2025). "Moreover, proteomic data from the CPTAC database demonstrated significant differences in PPIH protein levels between tumor and normal tissues across multiple cancer types." (PMID 40895540, 2025). "In addition to miRNAs, the expression levels of peptidylprolyl isomerase H (PPIH) have emerged as significant in the context of cancer prognosis." (PMID 39767561, 2024). "Furthermore, the secretion of PPIH by tumors suggests its role as a predictive biomarker for cancer, highlighting its possible involvement in the initiation and progression of malignancies." (PMID 39767561, 2024). "Moreover, the subtype-specific expression patterns observed across various cancers imply that PPIH may exert tissue- or context-dependent biological functions, providing a potential basis for patient stratification and precision therapy." (PMID 40895540, 2025). "Our findings propose that PPIH may serve as a valuable predictive biomarker in tumor patients, and its secreted protein could be a potential serum marker, providing insights into the role of PPIH in cancer development and progression." (PMID 38834966, 2024).
tumor (2 papers, 2024 to 2025). "In multiple malignancies, elevated PPIH expression is closely associated with unfavorable survival outcomes, suggesting its potential involvement in promoting tumor progression, therapeutic resistance, or immune evasion." (PMID 40895540, 2025). "Statistical analysis indicated that PPIH overexpression significantly enhanced tumor-associated biological behaviors in all functional assays, whereas PPIH knockout led to a marked reduction in cellular activity (p < 0.05)." (PMID 40895540, 2025). "To ascertain the potential of PPIH protein as a clinical tumor marker, we conducted an enzyme-linked immunosorbent assay (ELISA) to measure PPIH levels in serum samples from patients with LIHC, COAD, BC, and healthy controls, comprising 16 cases each." (PMID 38834966, 2024). "Its positive correlation with tumor stage in specific malignancies indicates that aberrant PPIH expression may be closely associated with tumor progression and aggressiveness." (PMID 40895540, 2025). "Second, its elevated expression in proliferating monocytes and macrophages raises the possibility that PPIH may be involved in modulating tumor-associated immune responses." (PMID 40895540, 2025). "Moreover, by integrating serological studies with conventional tumor markers for a joint diagnostic approach, we evaluated PPIH’s potential as a serological marker for solid tumors." (PMID 38834966, 2024). "Furthermore, we evaluated the feasibility and diagnostic efficacy of PPIH as a serum marker by integrating serological studies with established clinical tumor markers." (PMID 38834966, 2024). "Interestingly, PPIH methylation was also strongly associated with both immune cell infiltration and immune checkpoint gene expression, indicating its potential dual role in tumor progression and immune modulation." (PMID 40895540, 2025). "To further investigate the heterogeneity of PPIH expression within the tumor microenvironment of HCC, we analyzed single-cell RNA sequencing (scRNA-seq) data from the GEO database (GSE166635)." (PMID 40895540, 2025). "In summary, we found that PPIH is upregulated in common solid tumors and correlates with poor prognosis, possibly facilitating tumor development via the spliceosome pathway." (PMID 38834966, 2024). "Normal colon tissue and normal breast tissue showed weak PPIH staining, while tumor tissue showed moderate PPIH staining." (PMID 38834966, 2024). "Nonetheless, the expression and implications of PPIH in the etiology and progression of common solid tumors have yet to be explored, including its potential as a serum tumor marker." (PMID 38834966, 2024). "According to the set of semi-quantitative assessment criteria, PPIH staining was moderate in normal liver, while PPIH staining was strong in tumor tissue." (PMID 38834966, 2024). "This was complemented by empirical validations such as protein immunoassays and immunohistochemistry (IHC), confirming PPIH upregulation in tumor tissues." (PMID 38834966, 2024). "Additionally, cell-cell communication analysis reveals dual roles of PPIH-high malignant cells and proliferative myeloid cells in remodeling the tumor microenvironment." (PMID 40895540, 2025). "Notably, strong associations were observed between PPIH expression and lymphocyte populations such as Th1, Th2 (XCELL), and natural killer (NK) cells (EPIC), suggesting a key role for PPIH in shaping the tumor immune microenvironment (TME)." (PMID 40895540, 2025). "Collectively, our data suggest that aberrant PPIH expression may influence tumor cell proliferation, invasion, and metastasis by modulating these targets, warranting further verification." (PMID 38834966, 2024). "Furthermore, protein analysis in six LIHC patients (comprising six tumor tissues and six matched adjacent normal tissues) confirmed statistically significant higher levels of PPIH in LIHC tissues." (PMID 38834966, 2024). "IHC staining was conducted on paraffin-embedded tumor tissues to determine PPIH protein levels." (PMID 38834966, 2024).
tumor (continued). "Moreover, the significant enrichment of DNA replication and cell cycle-related pathways further suggests that PPIH may promote tumor cell proliferation by facilitating cell cycle progression." (PMID 40895540, 2025). "Meanwhile, we observed a significant overlap in the expression patterns of key cell cycle regulators, including CDC25C, CCNB1, and CDK1, with PPIH in malignant cells, further suggesting that PPIH may promote tumor cell proliferation by modulating cell cycle progression." (PMID 40895540, 2025). "Our analysis of PPIH co-expressed genes suggests a significant role in RNA binding, positing that elevated PPIH in tumor tissues and reduced serum levels might be attributable to PPIH’s interaction with circRNA, fostering tumor cell advantages while decreasing PPIH secretion." (PMID 38834966, 2024). "Together, these findings underscore the complexity of PPIH regulation in HCC and highlight its potential relevance in both tumor cell-intrinsic and microenvironmental contexts." (PMID 40895540, 2025). "The results demonstrated that PPIH expression may also significantly influence DFI and PFI in several tumor types." (PMID 40895540, 2025).
PPIH also shares sentences with these, for which no sentence is quoted: cholangiocarcinoma (1 paper); clear cell renal cell carcinoma (1); colorectal adenocarcinoma (1); colorectal cancer (1); COVID-19 (1); dental caries (1); endometrial cancer (1); esophageal cancer (1); head and neck squamous cell carcinoma (1); ovarian serous cystadenocarcinoma (1); prostate adenocarcinoma (1).